TREM1 (triggering receptor expressed on myeloid cells 1)
Diseases named in the same sentence as TREM1 in open-access papers (continued):
Sharing a sentence is not in itself a finding about the gene and the disease.
tumor (continued). "Following the significant TREM-1-induced reduction of Pan02 tumor growth in mice, we investigated the cellular and transcriptomic changes induced by TREM-1 activation by performing scRNA-seq." (PMID 40917508, 2025). "Here we performed a comprehensive analysis of the relation between TREM1 expression patterns and tumor microenvironments in OV and found that TREM1 was significantly positively correlated with Tregs and macrophage M2." (PMID 39744496, 2025). "Our findings establish TREM1 as a critical tumor-intrinsic regulator of LCSLC survival and tumorigenic potential, independent of its known immunomodulatory role in the TME." (PMID 40677705, 2025). "In contrast, these cells were significantly reduced in the adjacent normal tissue of LUSC and normal renal tissue, with markedly lower TREM1 expression levels compared to tumor tissue." (PMID 41413734, 2025). "TREM-1 activation using the agonistic antibody significantly reduced tumor growth compared to isotype control." (PMID 40917508, 2025). "This stark contrast in tumor initiation underscores the crucial role of TREM1 in driving the tumorigenicity of LCSLCs." (PMID 40677705, 2025). "In prostate cancer, androgen receptor signaling in macrophages drives TREM1-mediated tumor progression." (PMID 41394801, 2025). "In KIRC, TREM1+ PMN-MDSCs were found enriched in regions surrounding infiltrating epithelial/tumor cells and exhibited spatial co-localization with Tex cells and fibroblasts." (PMID 41413734, 2025). "While our lab has previously established the proinflammatory role of TREM1 in the tumor microenvironment (TME), its direct involvement in the cancer cells themselves, independent of its TME effects, has yet to be explored." (PMID 40677705, 2025). "In HCC prior publications have demonstrated that over expression of TREM1 can significantly enhance tumor cell proliferation and survival." (PMID 40677705, 2025). "Overall, these findings demonstrate that TREM-1 activation remodels innate and adaptive immune compartments in the Pan02 tumor, characterized by an expansion of activated CD8+ T cells while reducing immunosuppressive Tregs." (PMID 40917508, 2025). "Different studies have indicated that inhibitors such as SRI42127 can reduce the activation of TREM1 and limit the migration of myeloid cells to the site of the tumor, suggesting a promising strategy to control the progression of GBM." (PMID 40868137, 2025). "These inflammatory cytokines are likely to contribute to the TREM-1-induced reduction of tumor growth." (PMID 40917508, 2025). "Several studies have demonstrated that TREM-1 can promote tumor growth and progression by enhancing the immunosuppressive characteristics of the TME." (PMID 40917508, 2025). "Silencing TREM1 induces a shift from M2 to M1 polarization, reducing M2 markers and impairing tumor cell migration and invasion via suppression of the PI3K/AKT/mTOR pathway." (PMID 40764998, 2025). "TREM1+ fibroblasts, which progressively increased in tumor and metastatic tissues, expressed TREM1, a receptor classically involved in amplifying inflammatory responses." (PMID 41246350, 2025). "Elevated TREM-1 expression in human tumor-activated hepatic stellate cells (HSCs) has been correlated with poor survival outcomes in HCC patients, highlighting its potential as a key driver of disease progression." (PMID 41226426, 2025). "TREM1 is primarily expressed in myeloid cells (monocytes, macrophages, neutrophils) and possibly in malignant cells, although its exact role in tumor promotion is not yet well understood." (PMID 40677705, 2025). "Overall, these findings verified that TREM1 have a significant function in immune response and tumor development." (PMID 39744496, 2025). "Studies have shown that CD46 and TREM1 are highly expressed on the surface of a variety of tumor cells throughout the body." (PMID 40475017, 2025).
tumor (continued). "Altogether, these results show that intra-tumoral TREM-1 activation reduces tumor growth in Pan02 tumors, indicating a potential use for TREM-1 activation to treat PDAC." (PMID 40917508, 2025). "A recent study has demonstrated that IL1 secretion by TREM1-positive myeloid cells within a pro-inflammatory stromal niche can induce treatment resistance in tumor cells via NFkB27." (PMID 40021759, 2025). "TREM-1 inhibition with VJDT not only reduced tumor progression but also enhanced the effectiveness of PD-1 immune checkpoint blockade." (PMID 41226426, 2025). "We show that activating TREM-1 reprograms myeloid cells, transforms the tumor microenvironment, and boosts antitumor immunity, identifying TREM-1 as a promising immunotherapeutic target for treating PDAC." (PMID 40917508, 2025). "Remarkably, TREM-1L was more effective than agonistic TREM-1 antibody in both inducing in vitro cytokine production and reducing tumor growth in vivo." (PMID 40917508, 2025). "Blocking TREM-1 reduced Treg recruitment, suppressed tumor progression, and enhanced PD-L1 blockade efficacy." (PMID 40764998, 2025). "Tumor-bearing mice were treated with intra-tumoral injections of anti-TREM-1 antibody or TREM-1L on days 7 and 11 post-tumor inoculation." (PMID 40917508, 2025). "qPCR and western blot analysis results revealed that, compared with those in the NC group, both the mRNA and protein expression levels of TREM1 were significantly lower in the tumor tissues of mice in whichTREM1 was stably knocked down." (PMID 40551711, 2025). "Differential expression marker analysis revealed that Macs/Mono S7 cells specifically expressed SPP1 and TREM1, indicating similarity to SPP1+ tumor‐associated macrophages (TAMs)." (PMID 40432877, 2025). "TREM1 is a myeloid cell surface receptor involved in the tumor microenvironment, where it amplifies the inflammatory response and exhibits antitumor effects." (PMID 40853920, 2025). "To bridge this gap, we included a primary HCC patient tumor sample to examine TREM1 expression in CD133+EpCAM+ LCSLCs." (PMID 40677705, 2025). "Pharmacologic inhibition of TREM1 with VJDT recapitulated the tumor-suppressive effects observed in genetic models." (PMID 40677705, 2025). "This indicates that CD46 and TREM1 promote tumor proliferation and metastasis by inhibiting autophagy and apoptosis during OSCC development." (PMID 40475017, 2025). "Meanwhile, significant differences in METTL7B, HOXB8, and TREM1 were found between the controls and tumor samples in both mRNA levels." (PMID 38376699, 2024). "We found that TREM1 expression was negatively correlated with tumor purity (TCGA-seq: R= -0.7350, P <0.0001; CGGA-seq: R= -0.7126, P <0.0001) in the TCGA and CGGA datasets." (PMID 38370418, 2024). "We also observed that TREM1 was positively correlated with marker genes of tumor infiltrating cells, such as CD8+ T cell, NK cell, DC cell, and macrophage." (PMID 38370418, 2024). "In conclusion, TREM1 is mainly expressed by macrophages and is positively correlated with tumor immune escape." (PMID 38914803, 2024). "We identified the highest numbers of outgoing and incoming signaling interactions in BIT tumor state, TREM1 and TREM2 myeloid cells, and dendritic cells, with fewer interactions predicted from T cells and fibroblasts." (PMID 39289380, 2024). "Conversely, TREM1 gene expression was significantly upregulated in tumor samples compared to normal samples across various cancers." (PMID 39149674, 2024). "The TREM-1 levels were gradually upregulated along with the tumor grades and stage 3 to stage 4 in ccRCC." (PMID 37217993, 2023). "In patients with non-small cell lung cancer (NSCLC), TREM1 expression in TAMs correlates with tumor recurrence and poor survival." (PMID 37651197, 2023). "Their decrease in Trem1–/– mice suggests an attenuation of the cytokine/chemokine signaling network essential for tumor infiltration." (PMID 37651197, 2023).
tumor (continued). "Canonical pathways that were significantly enriched included fibrosis signaling, the tumor microenvironment pathway, estrogen receptor signaling, TREM1 signaling, ID1 signaling, STAT3 signaling, and HIF1 signaling." (PMID 38028629, 2023). "We have previously shown that FasL, present on the surface of TREM-1–induced lymphocytes, is necessary for the induction of a cytotoxic signal in tumor cells." (PMID 36653582, 2023). "First, although we confirmed that TREM-1 was highly expressed in tumor tissue compared with benign tissue, and the expression was positively correlated with Fuhrman grade, by immunohistochemistry experiment." (PMID 37217993, 2023). "As expected, TREM1 transcript levels were elevated in almost all human tumor cohorts compared with their corresponding normal tissues." (PMID 37651197, 2023). "We next examined the effect of TREM1 deficiency and its antagonism by VJDT on the tumor immune infiltrates." (PMID 37651197, 2023). "Our work highlights the ability of TREM1 inhibition in diminishing tumor progression and augmenting the efficacy of PD-1 immune checkpoint blockade." (PMID 37651197, 2023). "Within the canonical pathway analysis, we identified a sexually divergent induction of TREM1 signaling, NF-κB signaling, pathogen-induced cytokine signaling, and tumor microenvironment pathway." (PMID 36945656, 2023). "We validated that knockdown of TREM1 on HepG2 cells significantly restricted tumor growth compared with the control group." (PMID 37651197, 2023). "To further validate findings from the TCGA database, we analyzed TREM1 protein expression in selected human normal and tumor tissue sections by immunofluorescence staining." (PMID 37651197, 2023). "To better understand the impact of TREM1 in these 2 carcinomas, we identified genes that correlated with TREM1 expression in both tumor types." (PMID 37651197, 2023). "Silencing TREM1 in human tumor cells attenuates tumor growth in xenograft models and decreases cell proliferation and cell motility." (PMID 37651197, 2023). "Other tumors, such as GBM, exhibited high levels of TREM1 expression independent from their CD68+ microglial cells, indicating that these neoplasms were intrinsically TREM1 positive." (PMID 37651197, 2023). "This suggests the IL-8 and TREM1 gene expression seen in the MEC spots is from the proximity of hypoxia myeloid cells to MEC tumor cells in the regions of necrosis." (PMID 37694144, 2023). "TREM1 similarly appears to amplify the inflammatory response, including production of IL-6; blockade of TREM1 has reportedly attenuated tumor growth in an experimental PDAC model." (PMID 38028629, 2023). "In summary, data from our flow cytometry and scRNA-Seq analyses demonstrate that TREM1 inhibition alters the tumor immune landscape to limit MDSC frequency while boosting effector CD8+ T cell immunity to effectively augment PD-1 ICB therapy." (PMID 37651197, 2023). "To further characterize the tumor-promoting role of TREM1 in vivo, we performed xenograft studies using immunodeficient NSG mice." (PMID 37651197, 2023). "Overall, the results of these studies, along with our previous reports, prompted us to investigate the role of TREM1 in the crosstalk between tumor cells and the immune microenvironment." (PMID 37651197, 2023). "An increase in TNFAIP2, ICAM1, and ITGA5 expression pointed to a possible TREM1- and HuR-dependent formation of tertiary structures between tumor and myeloid-derived cells within the inflammatory peri-necrotic areas." (PMID 36249290, 2022). "Growing evidence suggests TREM-1 involvement in oncogenesis through cancer related inflammation and the surrounding tumor microenvironment." (PMID 35875168, 2022). "A subsequent analysis established the top 10 upregulated canonical pathways by the effect of LPS; granulocyte adhesion and diapedesis, IL-17 signalling, TREM1 signalling, and tumor microenvironment were observed in our study." (PMID 35002734, 2021).
tumor (continued). "TREM-1 expression was significantly correlated with tumor purity (r=-0.102, P<0.05) and the infiltration levels of the dominant immune cells." (PMID 34122331, 2021). "TREM-1 expression is positively correlated with immune infiltration, tumor progression and poor overall survival across cancers." (PMID 34122331, 2021). "In this study, TREM-1 signaling in TAMs was shown to impair anti-tumor activity of CD8+ T cells through the recruitment and activation of T-regs, thereby inducing resistance to anti-PD-L1 treatment." (PMID 34956864, 2021). "The presence of very numerous CD68± histiocytes in the tumour stroma directly relates to high infiltration by TREM-1± and by CD35± histiocytes (p = .026 and .005, respectively)." (PMID 33769181, 2021). "In surgical specimens, TREM1 expression varied among tumor molecular subtypes, with highest expression in the more aggressive subtypes (Basal-like, HER2-E)." (PMID 34956864, 2021). "By ranking tumor samples (columns) on TREM1 expression frequency in the myeloid compartment, a clear correlation was observed between the percentage of TREM1-expressing myeloid cells and the frequency and magnitude of expression of the target genes." (PMID 34956864, 2021). "Within molecular subtypes, TREM1 levels showed significant associations with DMFS in Basal-like, Luminal B (LumB) and Luminal A (LumA) tumor subtypes." (PMID 34956864, 2021). "In summary, we found that TREM-1 is highly expressed on myeloid cells in tumor-bearing mice and in patients with RCC and that TREM-2 is co-expressed with TREM-1 in MDSC and TAM." (PMID 35223446, 2021). "We confirmed these findings in human disease by demonstrating the expression of TREM-1 on tumor-infiltrating myeloid cells from patients with RCC and finding that sTREM-1 was increased in patients with RCC." (PMID 35223446, 2021). "TISIDB analysis showed that high expression of TREM-1 in the pan-cancer cohort was accompanied by a more advanced tumor stage and shorter OS time." (PMID 34122331, 2021). "Of 8 cell types identified by clustering, prevalent and high-level TREM1 expression was observed in the myeloid cell population (n=301 cells), while low-level TREM1 was observed sparsely in tumor cells and T cells." (PMID 34956864, 2021). "TREM1-silenced cells were injected into nude mice, and the tumor volume in vehicle-control group and ADI treatment group was monitored." (PMID 33664852, 2021). "Within the tumor site, the likely complex interactions between TREM-1-positive granulocytic cells and their TREM-2-expressing macrophages are yet to be fully dissected." (PMID 35223446, 2021). "The wound healing pathway was most significantly upregulated, followed by the tumor microenvironment (-log(p value): 9.99 and 8.12, respectively), whereas TREM1 signaling showed the highest z-score (3.58)." (PMID 34824220, 2021). "The same test shows statistically significant relationships between both p16 and TREM-1 and the cause of death (p = .034 and .001 respectively), and between peritumoral TREM-1 and death due to tumour." (PMID 33769181, 2021). "In accordance with our previous results demonstrating increased TREM-1 expression in Mo-MDSC during tumor progression, we found that Mo-MDSC were more suppressive than PMN-MDSC, inhibiting Con A-induced T cell proliferation at lower MDSC-to-splenocyte ratios." (PMID 35223446, 2021). "Its family member, triggering receptor expressed on myeloid cells 1 (TREM1), however, has been implicated to reduce tumor burden in PDA." (PMID 33782087, 2021). "Next, we stratified the 531 tumor cases into tertiles based on the RSEM gene expression values of Trem1 and then partitioned the patients into three groups: high (upper tertile), low (lower tertile), and NC (intertertile range as no change in expression)." (PMID 35223446, 2021). "Expression of TREM-1 was described to promote tumourigenesis and support tumour growth in various tumour models including intestinal-54, pancreatic- and lung cancer." (PMID 32908142, 2020).
tumor (continued). "After a longer time, the Th1 immunity is downregulated by the immunosuppressive activity of growing tumor cells so the antitumor activity of TREM-1 is diminished." (PMID 32684831, 2020). "Therapeutic effects of TREM-1 targeting will thus be ultimately dictated by the functional interplay among the different TREM-1+ immune cell populations recruited to tumor sites, suggesting that caution should be exerted in modulating its activity." (PMID 32456204, 2020). "TREM1 plays a disease-promoting role via amplifying inflammation, promoting lipid accumulation, hepatic fibrosis, and accelerating tumor progress." (PMID 33297569, 2020). "The results of Transwell and VM formation assays demonstrated that hypoxia-induced macrophages promoted U87 and LN229 tumor cell migration and vascular mimicry but that this effect was significantly reduced after knockdown of TREM1." (PMID 32765489, 2020). "At the beginning of tumor formation, this TREM-1 immunostimulatory activity has a positive function—it serves as an antitumor immune mechanism." (PMID 32684831, 2020). "In the process of promoting tumor formation, the role of TREM1 is based on the dysfunction of CD8+ T cell." (PMID 33297569, 2020). "Future studies will establish the role of TREM-1 in tumor growth and define the mechanisms by which TREM-1 modulates tumor growth." (PMID 32684831, 2020). "In detail, compared to the tumor-free colonic mucosa, TREM-1 expression is increased in both murine and human colorectal tumors, specifically within tumor-infiltrating neutrophils." (PMID 31546668, 2019). "The inhibitory effects of ApoE KO on tumor growth and metastasis were associated with an increased number of infiltrated immune cells, CD57+ NK cells, and TREM-1 expression at tumor tissues." (PMID 31275318, 2019). "A recent study demonstrated that expression of TREM-1 in mouse lungs was increased by tumor-specific knockout of autophagy-related gene." (PMID 31440123, 2019). "This study highlights hypoxia-induced tumor immunosuppression by TREM-1+ TAMs that attracts CCR6 + Foxp3 + Tregs, and TREM-1+ TAMs confers HCC resistance to Programmed cell death 1 ligand 1 (PD-L1) treatment." (PMID 31464625, 2019). "In vitro studies demonstrated that the expression of TREM-1 in macrophages in tumor microenvironment is dependent on COX-2 signaling." (PMID 29844416, 2018). "In contrast, TREM-1 was highly expressed on tumor-infiltrating Ly6G+ neutrophils which also represented the predominant myeloid cell subset in Trem1+/+ tumors." (PMID 29093489, 2017). "Analysis of tumor size distribution indicated that presence of TREM-1 mostly impacted on the incidence of small tumors (≤5 mm3) rather than affecting the growth of large tumors." (PMID 29093489, 2017). "Taken together, the flow cytometry analysis corroborated the notion that tumors of Trem1+/+ and Trem1−/− mice mostly differed in the extent of tumor-infiltrating neutrophils versus B cells." (PMID 29093489, 2017). "Gene expression analysis of Trem1−/− versus Trem1+/+ tumor tissue demonstrated distinct immune signatures." (PMID 29093489, 2017). "In particular, Trem1−/− mice exhibited reduced tumor numbers and load in an experimental model of inflammation-driven tumorigenesis." (PMID 29093489, 2017). "In contrast, TREM-1 was highly expressed by tumor-infiltrating neutrophils which represented the predominant myeloid population in Trem1+/+ but not in Trem1−/− tumors." (PMID 29093489, 2017). "Strikingly, in Trem1+/+ tumors the relative abundance of neutrophils was even further increased, with Ly6G+ neutrophils representing up to 40% of tumor-infiltrating CD45+ leukocytes." (PMID 29093489, 2017). "Our results demonstrated that the level of TREM-1 on CD45+CD14+ monocyte/macrophage from tumor tissue displays a significantly lower than that from corresponding distal nontumor lung tissues." (PMID 27244892, 2016).